ATM (ATM serine/threonine kinase)
Diseases named in the same sentence as ATM in open-access papers (continued):
Sharing a sentence is not in itself a finding about the gene and the disease.
ovarian carcinoma (continued). "Another clinical trial is aimed at targeting ATM deficient advanced lung adenocarcinomas as well as high grade ovarian cancers that harbor BRCA1/2 mutations using a combination of AZD6738 and carboplatin (NCT02264678)." (PMID 33498525, 2021). "ATM is a candidate ovarian cancer susceptibility gene due to its role in breast and pancreatic cancer." (PMID 33086730, 2020). "While monoallelic ATM germline PVs have been described in patients with ovarian cancer, heterozygous ATM variants have been associated predominantly with elevated BC incidence rather than other cancer types." (PMID 30086788, 2018). "Remarkably, 2 of the 3 ATM mutation carriers of our cohort have first-degree relatives presenting with ovarian cancer, one of whom harbors the additional CHEK2 exon 9–10 deletion." (PMID 30086788, 2018). "Lastly, in ovarian cancer models, key proteins that coordinate recognition of DNA damage, ataxia-telangiectasia mutated (ATM) and PARP-1, were induced." (PMID 29184090, 2017). "No data on the association of these polymorphisms and response to therapy in ovarian cancer have been reported yet, while few data on the ATM, ATR, Chk1 and Chk2 SNPs under study have been reported in other tumor types." (PMID 27905519, 2016). "Polymorphic variant p.Asp1853Asn in the ATM gene showed tendency towards increased risk of ovarian cancer for heterozygotes (OR 1.40; 95% CI 0.95-2.06; p = 0.091) and for the carriers of at least one minor A allele (OR 1.43; 95% CI 0.98-2.09; p = 0.061)." (PMID 25591549, 2015). "Various reports have shown the association of ATM mutation with risk of different human malignancies including breast, prostate, and ovarian cancers, mantle cell lymphoma, and B-cell chronic lymphocytic leukemia." (PMID 22414247, 2011). "Ataxia telangiectasia mutated (ATM) blockage can induce apoptosis in ovarian cancer." (PMID 40554491, 2025). "Individual reports usually focus on early-onset cases, and, while at least for other tumor types an earlier age of onset has been ascertained, some authors propose for ATM (and other moderate penetrance genes) an association mainly with late-onset ovarian cancer." (PMID 39984762, 2025). "Interestingly, ATM heterozygous variants have been associated to an increased risk of BC so that ATM is considered a moderate penetrance gene for hereditary breast and ovarian cancers." (PMID 36035419, 2022). "Women who test positive for an inherited pathogenic/likely pathogenic gene variant in BRCA1, BRCA2, PALB2, CHEK2 and ATM are at an increased risk of developing certain types of cancer—specifically breast (all) and epithelial ovarian cancer (only BRCA1, BRCA2, PALB2)." (PMID 35681696, 2022). "However, it should be noted that whilst ATM mutations are common in hematological malignancies, it has been predicted only 1–5% ovarian cancers contain somatic ATM mutations." (PMID 35954206, 2022). "Moreover, two cases of epithelial ovarian cancer and four cases of pancreatic cancer were detected in six carriers of ATM pathogenic or likely pathogenic germline variants." (PMID 33919281, 2021). "Preclinical observations indicate that the synthetic lethality of ATR or CHK1 inhibitors in ATM-deficient cancers may be a new opportunity for effective ovarian cancer therapy." (PMID 32316968, 2020). "Furthermore, ATM mutations have been found in ovarian cancer." (PMID 32756499, 2020). "Therefore, PARP inhibitors might provide a survival advantage to ATM-mutated ovarian cancer, especially for CCC and EC types and tumor sequencing might be important not to miss these somatic mutations." (PMID 31780705, 2019).
ovarian carcinoma (continued). "Six concordant P/LPGVs in ATM were identified in three patients with ovarian cancer and one each with pancreatic, thyroid, and non-small cell lung cancers, with the latter tumor type being a less common phenotype." (PMID 41465149, 2025). "In this study, ovarian cancer cells (SKOV3) were treated with an ATM inhibitor (KU60019) for 24 hours, and the fold changes of DGAT1 and hsa-miR-1273g-3p were quantified by real-time quantitative polymerase chain reaction (RT-qPCR)." (PMID 40554491, 2025). "In current study, we found that the expression of DGAT1 was significantly suppressed in ovarian cancer cell line SKOV3 cells after ATM inhibitor KU60019 treatment." (PMID 40554491, 2025). "In summary, we show that SETD1A loss renders ATM-deficient and BRCA1-mutated breast, lung, and ovarian cancer cells resistant to PARPi by restoring HR, and that this is partly driven by defective EME1 transcription." (PMID 39994444, 2025). "Ovarian cancers with high PRDX1/high ATM or high PRDX1/high MRE11 expression showed poor survival and an aggressive phenotype." (PMID 40387816, 2025). "Several oncogenes frequently mutated in endometrial and ovarian cancer (ARID1B, ATM, BRCA1, CHD2, POLE, and PMS2) were also present in LMS." (PMID 39691991, 2025). "Hsa-miR-1273g-3p mimics were used to investigate the relationship between DGAT1 and hsa-miR-1273g-3p in ovarian cancer cells under ATM inhibitor treatment, and cell apoptosis rate, viability, and migration were detected." (PMID 40554491, 2025). "Analysis of a clinical cohort of ovarian cancers treated with platinum chemotherapy revealed that tumours with high PRDX1/high ATM or high PRDX1/high MRE11 expression manifested aggressive phenotypes and poor patient survival." (PMID 40387816, 2025). "It has been also demonstrated that the tumor expression of ATM protein expression correlates with prognosis in ovarian cancers." (PMID 39984762, 2025). "It has been recently reported that an orally bioavailable dual inhibitor of ATM and DNA-PKcs kinases synergized with PARP inhibitors in BRCA1/2-deficient models, including UWB1.289, a BRCA1-mutant human ovarian cancer cell line." (PMID 39594684, 2024). "The overexpression of this miRNA in ovarian cancer cells inhibits cell proliferation, invasion, and migration; induces apoptosis; and arrests the cell cycle in the G1 phase by targeting ATM." (PMID 38793064, 2024). "Of particular significance, ATMIN (ATM-INteracting protein, also known as ASCIZ (ATM/ATR substrate Chk2-interacting Zn2+-finger protein)) was frequently deleted in bBRCA1 ovarian cancers, with a prevalence of 68%." (PMID 39198848, 2024). "For carriers of ATM PGV, risk is described as: (i) an absolute risk of BC ranging from 20 to 40% and (ii) an absolute risk of epithelial ovarian cancer ranging from 2 to 3%." (PMID 38672070, 2024). "Among 26 genes included in the KSA extended breast and ovarian cancer panel, ATM was also the gene in which the highest number of VUS was detected at 32%." (PMID 36647026, 2023). "The tropomyosin inhibitors, for example, tropomyosin inhibitor ATM-3507, prolonged vinorelbine-induced mitotic arrest in ovarian cancer cells." (PMID 37833976, 2023).
ovarian carcinoma (continued). "A recent review pointed out the predominance of deleterious variants in breast and ovarian cancer genes among PanC patients, with BRCA2 and ATM having the highest prevalence of pathogenic mutations in both sporadic and unselected PanC." (PMID 36717774, 2023). "Breast cancer susceptibility gene 1 (BRCA1) is a key member of the ATM-mediated DDR and directs the homologous recombination repair (HR) pathway, and mutations in this gene are associated with ovarian cancers." (PMID 38137018, 2023). "This study demonstrates that, among patients with breast or ovarian cancer, positive genetic test results in ATM, CHEK2, PALB2, and other DDR genes impact clinical recommendations for the majority of patients and/or their family members." (PMID 35626031, 2022). "Pathogenic variants in PALB2, ATM and BARD1 are recognized by the NCCN as involved in hereditary breast and ovarian cancer syndrome but have insufficient evidence to determine their ovarian cancer risk." (PMID 35159349, 2022). "In ovarian cancer patients, ATM germline PVs were found in 0.64–0.87% of cases, which was significantly greater than the 0.19% frequency in the controls from the Exome Aggregation Consortium." (PMID 35008949, 2022). "In this study, we investigated the role of miR-542-5p in the presence of an ATM inhibitor (KU60019) in SKOV3 ovarian cancer cells, which are widely used to investigate DNA damage response pathway-related genes." (PMID 35795059, 2022). "Mutations of other genes in the Fanconi anemia pathway also confer increased ovarian cancer risk, including PALB2; ATM; RAD51C/D; and BRIP1." (PMID 35159349, 2022). "Currently, the ATM gene is included in nearly all multigene panels used in genetic testing for hereditary breast and ovarian cancer." (PMID 35008949, 2022). "We attribute the differences in the results between U2OS and SKOV3 cells to the higher resistance of SKOV3 to PARP inhibitors and to the higher ATM activity previously reported in ovarian cancer cells." (PMID 36233063, 2022). "It was reported that ovarian cancer cells in general show higher ATM level/activity than normal cells." (PMID 36233063, 2022). "Similar results were observed using combined ALDH and ATM/ATR inhibitors in HR-proficient ovarian cancer cells, substantiating ALDH1A1 and related enzymes as a potential target for therapy." (PMID 35205643, 2022). "Among the FPC cohorts, ATM (3.09%) and BRCA2 (2.61%), two genes associated with breast and ovarian cancer, had the highest prevalence of PVs followed by CDKN2A (2.24%), the major high-risk susceptibility gene involved in familial melanoma." (PMID 34255164, 2021). "Among the four cases of patients with ovarian cancer, we found a Pathogenic variant in RAD51C, 2 VUSs, respectively in ATM and RAD50 genes, and a Likely-benign variant in STK11." (PMID 34299313, 2021). "It was reported that ATM mediated the Akt/GSK-3β/Snail signaling pathway in ovarian cancer cells (A2780, Hey, HeyA8, SKOV3, SKOV3ip1, OVCA433 and OVCA429 cell lines), xenograft mouse models of ovarian cancer and high grade serous ovarian cancer patients." (PMID 33802884, 2021). "In our population, accordingly, ATM families exhibited ovarian cancer in 21% of cases and pancreatic cancer in 15.8% of cases, besides gastric, kidney/bladder and colon tumors." (PMID 33919281, 2021). "In our case-control analyses with a non-cancer east-Asian population and non-cancer females, we found significant prevalence of PALB2, BARD1, BLM, and ATM mutations in our HBOC cohort, including patients with ovarian cancer." (PMID 32566746, 2020).
ovarian carcinoma (continued). "Our study shows that PTFSs increase the phosphorylation of ATM at Ser1981, histone H2A.X at Ser139, and Chk2 at Thr68, which suggests that a DNA double-stranded break developed in ovarian cancer cells." (PMID 32560563, 2020). "In this study, we aim to gain insight in the germline mutation spectrum of ATM, BARD1, BRIP1, ERCC4, PALB2, RAD51C and RAD51D in breast and ovarian cancer families from Spain." (PMID 32756499, 2020). "Another study of high AA dosage on ovarian cancer cells observed induction of DNA damage, depletion of cellular ATP, and activation of the corresponding stress signaling kinases, ATM (ataxia telangiectasia mutated) and AMPK (AMP-activated protein kinase)." (PMID 30695991, 2019). "Here, we focused on the top 15 enriched signaling pathways, e.g., axon guidance signaling, Wnt/β-catenin signaling, ephrin receptor signaling, ATM signaling, ovarian cancer signaling, and SAPK/JNK signaling." (PMID 31664600, 2019). "The carrier of both the ATM frameshift and BRCA2 K3326* variants developed both breast and ovarian cancer." (PMID 28591191, 2017). "We next tested the endogenous basal level of Wip1 and pAKT, SNAIL, p-ATM, E-cadherin in the ovarian cancer cell lines." (PMID 27121065, 2016). "We here report the retrospective analysis of polymorphisms in 5 genes (ATM, ATR, Chk1, Chk2 and CDK12) involved in the cellular response to platinum in a cohort of 240 cancer patients with late stage ovarian cancer." (PMID 27905519, 2016). "Our results suggest that Wip1 inhibits ovarian cancer metastasis through the ATM/Akt/Snail mediated signaling." (PMID 27121065, 2016). "Beyond the high penetrance BRCA1/2 genes, mutations of several cancer susceptibility genes, including ATM, CHK2 and PALB2, have been shown to associate, with a moderate penetrance, with familial breast and/or ovarian cancers." (PMID 27599564, 2016). "Three (23%) of the 13 PDAC patients with a personal history of breast or ovarian cancer had deleterious mutations, two BRCA2 mutations and one ATM mutation, the latter of which was described in the previous section (NCCH-16)." (PMID 27732944, 2016). "In univariate analysis, high ATM, high DNA-PKcs and high ATR expression are associated with poor ovarian cancer specific survival (OCSS) and progression free survival (PFS)." (PMID 26674120, 2014). "Here, we have conducted an exploratory stratification analysis based on XRCC1 status and ATM/DNA-PKcs/ATR expression in ovarian cancer." (PMID 26674120, 2014). "Since ovarian cancer stem cells express high levels of ATM, the role of ATM in carboplatin-resistant ovarian cancer awaits further verification." (PMID 25010594, 2014). "It is intriguing that the MSeA and carboplatin co-treatment differentially activates ATM and DNA-PKcs kinases, but inhibition of their kinase activities does not impact on the synergism of MSeA and carboplatin in killing the ovarian cancer cells." (PMID 25010594, 2014).
ovarian carcinoma (continued). "ATM +/XRCC1 +, DNA-PKcs +/XRCC1 + and ATR +/XRCC1 + tumours have significantly worse ovarian cancer specific survival and progression free survival compared to tumours that are ATM-/XRCC1-, DNA-PKcs-/XRCC1- and ATR-/XRCC1- respectively (ps ≤ 0.001)." (PMID 26674120, 2014). "High ATM nuclear expression in tumours showed an adverse clinical outcome with poor ovarian cancer specific survival (p = 0.01) and progression free survival (p = 0.026) compared with tumours that had low ATM expression." (PMID 26674120, 2014). "This may be due to impaired cytokinesis when Tpm3.1/3.2 function is inhibited by ATM-3507, as has been observed in ATM-3507-treated ovarian cancer cells." (PMID 41268543, 2025). "ATM inhibition is also effective in the treatment of ovarian cancer, targeting ATM might be a potential strategy for anti-cancer therapy." (PMID 40554491, 2025). "In the current study, we hypothesized that blocking DGAT1 might inhibit tumor growth, and investigated the role of DGAT1 in ovarian cancer cells in the context of ATM blockage in vitro." (PMID 40554491, 2025). "In this study, we focused on GC-5′ss-exons of the breast and/or ovarian cancer (BOC) susceptibility genes, i.e., ATM (MIM#607585) exon 50, BRIP1 (MIM#605882) exon 1, and PALB2 (MIM#610355) exon 12, the last of which specifically undergoes skipping as a frequent alternative splicing event." (PMID 39518003, 2024). "In their latest update, the National Comprehensive Cancer Network (NCCN) guidelines, although suggesting a strong association between high-risk ATM mutations (c.7271T > G) and both breast and ovarian cancer, do not recommend any risk-reducing surgery." (PMID 39543654, 2024). "The German Consortium for Hereditary Breast and Ovarian Cancer similarly states that a heterozygous mutation in the ATM gene should not be considered a contraindication to radiotherapy." (PMID 38393398, 2024). "In the Phase IIb tumour-agnostic JAVELIN BRCA/ATM study evaluating the same combination, durable responses were more common in BRCA-associated tumour types (including breast and ovarian cancers) than other tumour types, but the confirmed ORR of 26% was below the pre-specified 40% threshold." (PMID 38971950, 2024). "Clinically, the higher the ATM level was, the more aggressive the ovarian cancer would be." (PMID 36233063, 2022). "However, patient adherence rates across all patients and their relatives indicate that identifying P/LP variants in ATM, CHEK2, PALB2, and other DDR genes associated with increased risk of breast and ovarian cancer also impact patient care." (PMID 35626031, 2022). "However, the indications for PARPi are broader for patients with other cancer types (e.g., prostate and ovarian cancer), involving additional biomarkers (e.g., ATM, PALB2, and CHEK) and genomic instability scores." (PMID 36077867, 2022). "In addition, BRCA1/2, ATM, BRIP1, PALB2, RAD51C, and RAD51D gene mutations are reported to be associated with high risk of ovarian cancers, and from the results of tumor tissue, it is easy to further determine their genetic status." (PMID 35186721, 2022). "In our study, we also observed a decrease in mRNA and protein expression for ATM in patients with ovarian cancer, which may indicate a worse prognosis for their survival." (PMID 35807169, 2022). "Thus, our findings expand on the basic theory of the ATM inhibition as an anti-cancer strategy, and provide novel insight for therapeutic interventions in ovarian cancer." (PMID 35795059, 2022).